RPS3AP26 (RPS3A pseudogene 26)
Synonyms: RPS3A_11_824
Gene: Processed pseudogene on chromosome 7 (98,385,801 to 98,386,584, reverse strand). Ensembl gene ENSG00000214389.
Diseases named in the same sentence as RPS3AP26 in open-access papers:
RPS3AP26 is named in the same sentence as 1 disease in open-access papers, as found by Europe PMC text mining. Sharing a sentence is not in itself a finding about the gene and the disease. The quoted sentences say what the papers report.
infection (1 paper, 2025). The state of being infected such as from the introduction of a foreign agent such as serum, vaccine, antigenic substance or organism. "In contrast, genes such as RNA5S9, RPL7B9, MIR3609, RPS3AP26, and RPL21P16 were commonly found among the top ten differentially expressed genes in both the 16-week post-infection (16wpi) and 24-week post-infection (24wpi) patient groups." (PMID 41141600, 2025).